RNU2-40P (RNA, U2 small nuclear 40, pseudogene)
Gene: Small nuclear RNA gene on chromosome 4 (65,807,240 to 65,807,435, reverse strand). Ensembl gene ENSG00000222765.
Homologues: Orthologues: chimpanzee U2 (99% identical), macaque U2 (84% identical), mouse Gm24763 (67% identical), guinea pig U2 (55% identical), dog U2 (28% identical). Paralogues in human: RNU2-14P (73% identical), RNU2-36P (72% identical), RNU2-2 (71% identical), RNU2-48P (70% identical), RNU2-59P (70% identical), RNU2-3P (69% identical), RNU2-62P (69% identical), U2 (69% identical), RNU2-23P (68% identical), RNU2-6P (67% identical), RNU2-56P (67% identical), RNU2-26P (66% identical), and 66 more.